SLC5A1 (solute carrier family 5 member 1)
Diseases named in the same sentence as SLC5A1 in open-access papers (continued):
Sharing a sentence is not in itself a finding about the gene and the disease.
insulinoma (1 paper, 2025). "The loss-of-function mutation in SGLT-1 due to an SLC5A1 gene mutation may impact pancreatic β-cell plasticity, potentially contributing to insulinoma development through altered glucose homeostasis." (PMID 40662130, 2025).
melanoma (1 paper, 2023). A malignant, usually aggressive tumor composed of atypical, neoplastic melanocytes. "For instance, inhibition of miR-137 and miR-9 enhanced RSL3-induced ferroptosis in melanoma by targeting SLC5A1 and GOT1, respectively, in the glutamine metabolism pathway." (PMID 37626043, 2023).
cancer (48 papers, 2009 to 2025). A tumor composed of atypical neoplastic, often pleomorphic cells that invade other tissues. "Previous studies reported that SLC5A1 is associated with proliferation, migration, apoptosis, resistance to platinum-based chemotherapeutics, and poor prognosis in cancer cases 29-32." (PMID 39781340, 2025). "Wound healing and transwell assays revealed that oe-SLC5A1 significantly enhanced cell migration and invasion in both cancer cell types." (PMID 39781340, 2025). "PNLDC1, SLC5A1, and SYNM were then identified as hub genes that were associated with both platinum response status and prognosis, which was further validated by the Fudan University Shanghai cancer center (FUSCC) cohort." (PMID 35361267, 2022). "TTBK2 may also be involved in anti-cancer drug resistance: TTBK2 increases the cell surface number of sodium-coupled glucose transporter (SLC5A1) in cancer cells and confers cell survival against anti-cancer drugs." (PMID 24808823, 2014). "Consequently, medications that inhibit or reduce SLC5A1 activity may be effective in cancer treatment." (PMID 39781340, 2025). "Thus, we hypothesized that Hesperidin could inhibit cancer malignant progression by reducing SLC5A1 levels." (PMID 39781340, 2025). "In our analysis of the TCGA database, we found that SLC5A1 and SLC5A2 gene expression increased in CCA, consistent with the findings observed in other types of cancers." (PMID 39940750, 2025). "The gene expression of SLC5A1 and SLC5A2 and the protein expression of SGLT1 and SGLT2 have increased in several cancer cell lines and human cancer tissues." (PMID 39940750, 2025).
tumor (36 papers, 2009 to 2025). "The findings revealed that elevated SLC5A1 expression was significantly correlated with tumor pathological stage (p = 0.013) and vascular invasion (p = 0.033)." (PMID 39781340, 2025). "On the other hand, SLC6A20, SLC5A1, SLC4A4, and SLC16A10 were positively associated with OS in 3 tumor types." (PMID 37397501, 2023). "Interestingly, SLC6A14, SLC34A2, and SLC5A1 also resulted among the top DEGs SLC when comparing each TCGA tumor type with matched normal tissue." (PMID 37397501, 2023). "Furthermore, supported by bioinformatics analysis, the level of SLC5A1 in PDAC tumour tissue was higher than that in normal tissue in two of the three GEO series and in the Pei Pancreas dataset from the Oncomine database." (PMID 35090421, 2022). "Through univariate analysis, it was found that residual tumour status (R1 and R2) was a predictive factor for a shorter OS (HR = 1.765, 95% CI 1.104-2.822, P = 0.018), and high SGLT-1 (SLC5A1) expression (HR = 0.593, 95% CI 0.369-0.953, P = 0.031) was an independent factor for a longer OS." (PMID 35090421, 2022). "SLC5A1, also known as sodium/glucose transporter 1 (SGLT1), is highly expressed in various tumors and contributes to the uptake of glucose by tumor cells, supporting their glycolytic metabolism." (PMID 38373930, 2024). "The genes with low expression in the tumor group were CRISP3, FAM3D, SCNN1B, CRISP2, RBM20, PHYHIP, C2orf54, SLC5A1, PTCRA, C15orf59, and ANO10." (PMID 35389773, 2022). "Reportedly, glucose and amino acids are increased in tumor cells to meet the increased demand for robust proliferation, for example, by the induction of SLC2A1 and SLC5A1 for glucose, and by the induction of SLC7A5 for amino acids." (PMID 24718268, 2014). "Through univariate analysis, it was found that residual tumour status (R1 and R2) was a predictive factor for a shorter OS (HR = 1.683, 95% CI 1.040-2.723, P = 0.034), and high SGLT-1 (SLC5A1) expression (HR = 0.533, 95% CI 0.328-0.866, P = 0.011) was an independent factor for a longer OS." (PMID 35090421, 2022). "The Oncomine database indicated that SLC5A1 mRNA levels were significantly higher in tumours in the Pei Pancreas dataset (P = 0.033) but not in the Badea Pancreas dataset (P = 0.429)." (PMID 35090421, 2022). "The fact that MYC controls glutamine uptake and catabolism through transcription of SLC3a2, SLC5A1, SLC7A1, and GLS1 in tumor cells indicates that additional signaling events are involved in determining the target preference of MYC between tumor cells and activated T cells." (PMID 28245597, 2017).
infection (21 papers, 2014 to 2026). The state of being infected such as from the introduction of a foreign agent such as serum, vaccine, antigenic substance or organism. "In addition, higher expression of solute carrier family genes (Slc13a1, Slc26a3, Slc2a2, Slc40a1, Slc5a1, and Slc6a19) was seen in the gastric tissue of Muc1−/− mice compared with WT at sham and 8 h infection." (PMID 32793510, 2020).
cardiac diseases (5 papers, 2015 to 2025). "In contrast to SGLT2, which is not present in the heart, two other members of the SLC5A gene family, namely SGLT1 (SLC5A1) and the sodium-myoinositol cotransporter-1 (SMIT1, SLC5A3) are expressed in the heart and have been shown to contribute to Na+ influx in cardiac disease." (PMID 34360742, 2021).
genetic disease (3 papers, 2023 to 2024). "The importance of SGLT1’s transport capacity for water is highlighted by mutations of the SLC5A1 gene that result in a genetic disorder of glucose-galactose malabsorption." (PMID 37513169, 2023).
SLC5A1 also shares sentences with these, for which no sentence is quoted: Hyperglycemia (55 papers); Hypoglycemia (23); myocardial infarction (17); breast carcinoma (15); cardiomyopathy (13); Insulin resistance (12); Stroke (12); cardiac hypertrophy (11); chronic kidney disease (11); ischemia (10); type 1 diabetes (10); cardiovascular disease (9); metabolic syndrome (9); myocardial ischemia (9); COVID-19 (7); Hypertension (7); metabolic disease (7); hepatocellular carcinoma (6); ischemic cardiomyopathy (6); cervical cancer (5); cyst (5); lung carcinoma (5); Myocardial fibrosis (5); atherosclerosis (4); cervical tumors (4); endothelial dysfunction (4); ischemic heart disease (4); Alzheimer disease (3); Cerebral ischemia (3); Diabetic nephropathy (3).
A further 106 diseases each share a sentence with SLC5A1 in 3 papers or fewer.